SSB (small RNA binding exonuclease protection factor La)
Diseases named in the same sentence as SSB in open-access papers (continued):
Sharing a sentence is not in itself a finding about the gene and the disease.
pemphigus (1 paper, 2024). Pemphigus is a group of rare autoimmune diseases that cause blistering of the skin and mucous membranes (mouth, nose, throat, eyes, and genitals).This conditioncan occur at any age, but often strikes people in middle or older age. "As expected, patients with SLE displayed autoantibodies to nuclear antigens including SSA (Ro), SSB (La), Smith, and RNP, whereas patients with pemphigus and MS had few such autoantibodies." (PMID 38833310, 2024).
psoriasis (1 paper, 2025). An autoimmune condition characterized by red, well-delineated plaques with silvery scales that are usually on the extensor surfaces and scalp. "Positivity for anti-U1-RNP (66.7%; 8/12), anti-SSA (58.3%; 7/12) and anti-SSB (58.3%; 7/12) was frequent among patients with comorbid psoriasis." (PMID 40473266, 2025).
purpura (1 paper, 2025). A small blood vessel hemorrhage into the skin and/or mucous membranes. "In March 2021, the volunteer was diagnosed with SS due to positive anti-SSB antibodies, lymphocyte infiltration in the lip gland, dry eyes, and a large area of purpura in both lower limbs." (PMID 39931068, 2025).
ROSAH syndrome (1 paper, 2022). "Specifically, relevant to the poor dentition observed in patients with ROSAH syndrome, patients had normal IgA levels and lacked anti-SSA and anti-SSB antibodies." (PMID 35868845, 2022).
SAPHO syndrome (1 paper, 2021). SAPHO syndrome (acronym for Synovitis, Acne, Pustulosis, Hyperostosis and Osteitis) is an auto-inflammatory disease, mainly characterized by the association of neutrophilic cutaneous involvement and chronic osteomyelitis. "Besides, in terms of their low positive rate, the diagnostic value of anti-SSA and anti-SSB antibody should be reconsidered in patients with SAPHO syndrome." (PMID 33761629, 2021). "Compared with SSA or SSB antibody testing, objective ophthalmic and dental tests, as well as glandular biopsy might be of greater diagnostic value for SS with comorbid SAPHO syndrome." (PMID 33761629, 2021). "Our study exhibited only a 20% prevalence of anti-SSA and anti-SSB antibody in patients with coexistence of SAPHO syndrome and SS." (PMID 33761629, 2021).
Sinus bradycardia (1 paper, 2025). Bradycardia related to a mean resting sinus rate of less than 50 beats per minute. "Recent studies have shown that sinus bradycardia is a definite and persistent manifestation of maternal anti-SSA and anti-SSB antibody involvement in the fetal heart, either purely or in combination with AVB." (PMID 40589968, 2025).
synovitis (1 paper, 2008). Inflammation of a synovial membrane. "In addition, anti-SSB positivity was weakly and inversely associated with the prevalence of synovitis." (PMID 18462485, 2008). "The prevalence of anti-SSB is higher in pSS, but in our patient cohort it was also inversely related to the presence of synovitis." (PMID 18462485, 2008). "An exact logistic regression analysis was used to model the effects of the presence of positive anti-CCP antibodies on the prevalence of synovitis, adjusting for the potential covariates of age, disease duration, gender, and anti-SSA and anti-SSB antibodies." (PMID 18462485, 2008).
tuberculosis (1 paper, 2023). A chronic, recurrent infection caused by the bacterium Mycobacterium tuberculosis. "An orbital inflammation laboratory workup including a thyroid panel, amylase, antinuclear antibody, anti-thyroid peroxidase, anti-SSA/Ro, anti-SSB/La, antineutrophil cytoplasmic antibodies, tuberculosis QuantiFERON Gold were obtained to evaluate for autoimmune and infectious etiologies." (PMID 37173558, 2023).
ventricular septal defect (1 paper, 2025). The presence of a defect (opening) in the septum that separates the two ventricles of the heart. "Besides these immunological abnormalities, the patient was also positive for anti-SSA and anti-SSB antibodies and had a prior pregnancy complicated by suspected fetal ventricular septal defect, a high-risk factor." (PMID 41451211, 2025).
viral C hepatitis (1 paper, 2009). "The anti-SSA and/or anti-SSB Ab tests and the focus score were negative, but one of these five (not the patient with viral C hepatitis-associated sicca symptoms) had Bm2+Bm2′/eBm5+Bm5 ⩾5." (PMID 18782791, 2009).
vitiligo (1 paper, 2021). Generalized well circumscribed patches of leukoderma that are generally distributed over symmetric body locations and is due to autoimmune destruction of melanocytes. "To study the other components of ABs, in addition to vitiligo autoantigens, we used some antibodies against nuclear antigens, including histone 1 (H1), histone 2A (H2A), and ribonucleoprotein La/SSB, which were detected by Western blot." (PMID 34745423, 2021).
cancer (16 papers, 2009 to 2025). A tumor composed of atypical neoplastic, often pleomorphic cells that invade other tissues. "In addition, the SSB protein has RNA chaperone activity that promotes the processing of noncoding precursor RNAs but also stimulates the translation of selective mRNAs that encode cancer-promoting and antiapoptotic genes." (PMID 36785788, 2023). "Aberrant expression of SSB proteins contributes to increased cancer cell proliferation, migration, invasion, and chemoresistance and promotes tumor growth in mice." (PMID 36785788, 2023). "As a marker of treatment‐induced cancer cell death, we have developed a radiodiagnostic imaging antibody, which binds to La/SSB." (PMID 34636174, 2022). "La/SSB is an essential, ubiquitous ribonuclear protein, which is over expressed in cancer and plays a role in resistance to cancer therapies." (PMID 34636174, 2022). "The Small RNA Binding Exonuclease Protection Factor La (LARP3), which is a member of the La-related protein family, shows important cellular regulatory functions and has been reported to be associated with various diseases, including cancer." (PMID 39823419, 2025). "Our current study evaluated the significance of disparities in the levels of ANA, anti-dsDNA, anti-Sm, anti-RO52, anti-RO60, anti-SSB, anti-Nuc, anti-His, anti-Rib, and anti-nRNP antibodies between the cancer group and the cancer-free control group at the time of cancer diagnosis." (PMID 32586407, 2020). "Similarly, the discovery of autoantibodies including La/SSB-specific autoantibodies in sera of cancer patients suggests that autoantibodies also arise as a result of inefficient in vivo clearance of dying cancer cells." (PMID 19247485, 2009). "However, the role of SSB was still unclear in human cancers." (PMID 35096829, 2021). "It has been previously reported that the immunogenicity of cancer cell could induce the production of a wide range of auto-antibodies including ANA, anti-dsDNA, anti-Sm, anti-SSA, anti-SSB, anti-Rib, and anti-nRNP." (PMID 32586407, 2020). "The biggest differences between anti-CCP-negative and healthy donors were found for SSB (121-fold), cancer/testis antigen 47A (23-fold), and glutathione S-transferase theta-1 (18-fold)." (PMID 32486012, 2020). "Human Y RNAs interact with the autoimmune proteins SSB and RO60 that together form a ribonucleoprotein (RNP) complex termed RoRNP and Y RNAs also perform regulatory roles in DNA and RNA replication and stability, which has major implications for diseases including cancer." (PMID 35354369, 2022).
connective tissue diseases (16 papers, 2008 to 2025). "Frequency of IgE anti-SSA/Ro52-, -SSA/Ro60-, and -SSB/La-antibodies in patients with different connective tissue diseases and controls." (PMID 40181984, 2025). "Other antibodies that are more frequently associated with cardiac manifestation in IIM patients are anti Jo1 anti bodies (33.3%) and anti SSA/SSB antibodies (33.3%), but heart involvement in connective tissue diseases is still an undervalued field and in great need of further studies." (PMID 39596941, 2024). "Positive results for SSA Ro, SSB La, RNP/Sm, and Jo‐1 demonstrated a connective tissue disorder with higher mean values of BUN than the control group." (PMID 41131836, 2025). "However, the isolated detection of anti‐SSA/Ro or anti‐SSB/La antibodies is not enough to diagnose SS, since these antibodies may also appear in other connective tissue disorders or in healthy people." (PMID 40656544, 2025).
tumor (8 papers, 2009 to 2023). "During apoptotic tumour cell death in vitro, the La/SSB protein translocates from nucleus to cytoplasm, and as necrosis develops with loss of cell membrane integrity, the La/SSB protein becomes available for antigen‐specific antibody binding in the dead tumour cells." (PMID 34636174, 2022).
infection (6 papers, 2021 to 2026). The state of being infected such as from the introduction of a foreign agent such as serum, vaccine, antigenic substance or organism. "We consider the SSB as a new potential target to inhibit the infection of SARS-CoV-2." (PMID 37314180, 2023). "Its ability to mount antigen-specific responses to virally vectored CP312R and its SSB core site may contribute to the prevention of ASFV DNA replication during the virus’s infection in host cells." (PMID 36851771, 2023). "Patients with MIS-C have high levels of certain antibodies against autoantigens (anti-SSB, anti-Jo-1), lending credence to the hypothesis that MIS-C is mediated by a persistent autoimmune response to the original infection." (PMID 34356552, 2021).
mouth (6 papers, 2021 to 2025). "The disease is characterised by dry mouth and/or eye symptoms, lymphocytic infiltration of the affected glands, and the presence of autoantibodies, such as anti-Ro/SSA and anti-La/SSB antibodies." (PMID 33658234, 2021).
hematologic disorder (3 papers, 2011 to 2024). A disease involving the hematopoietic system. "Large sample studies are needed to clarify the real association between the hematological disorders and anti-SSB antibody." (PMID 24864270, 2014).
cardiovascular disease (2 papers, 2019). "Others and we have previously noted that SSA/SSB antibodies are associated with a less severe SLE, with less renal manifestations and reduced risk for cardiovascular disease and mortality." (PMID 30777133, 2019).
Musculoskeletal Diseases (2 papers, 2024 to 2025). "The 2020 American College of Rheumatology Reproductive Health Management Guidelines for Rheumatoid and Musculoskeletal Diseases recommend HCQ treatment for all pregnant women positive for anti-SSA/Ro-and/or anti-SSB/La antibodies to reduce CHB risk." (PMID 40066690, 2025). "The 2020 American College of Rheumatology Reproductive Health Management Guidelines for Rheumatoid and Musculoskeletal Diseases conditionally recommend hydroxychloroquine (HCQ) treatment for all pregnant women with positive anti-Ro/SSA and/or anti-La/SSB antibodies to minimize the risk of ACHB." (PMID 38167489, 2024). "The 2020 American College of Rheumatology Guideline for the Management of Reproductive Health in Rheumatic and Musculoskeletal Diseases recommends that lupus patients should be screened for anti-Ro/SSA and/or anti-La/SSB antibodies before or during pregnancy." (PMID 38167489, 2024). "The 2020 American College of Rheumatology Guidelines for the Management of Reproductive Health in Rheumatic and Musculoskeletal Diseases recommend 4 mg/day oral dexamethasone for pregnant women positive for anti-SSA/Ro and/or anti-SSB/La antibodies, with UCG suggesting CHB presence in the foetus." (PMID 40066690, 2025).
peripheral neuropathy (2 papers, 2023 to 2024). A disorder affecting the peripheral nervous system. "By logistic regression analysis, hyperglobulinaemia, RF, and anti-SSB antibodies were independent risk factors for the development of peripheral neuropathy in PSS (P < 0.05)." (PMID 36717930, 2023).
heart disease (1 paper, 2021). "She had no structural heart disease, and the serology surveys for autoantibodies including SSA/Ro and SSB/La were all negative." (PMID 34572222, 2021).
immune dysfunction (1 paper, 2019). "In our study, pSS patients had multiple autoantibodies such as anti-SSA, anti-SSB, and ANA antibody, suggesting that pSS with renal abnormalities may be related to immune dysfunction." (PMID 30906788, 2019).
inflammatory myopathies (1 paper, 2025). "Additionally, anti-SSA/Ro, anti-SSB/La, or anti-Ro52 positivity was also linked to higher ILD prevalence in other disorders, such as inflammatory myopathies." (PMID 40565330, 2025).
SSB also shares sentences with these, for which no sentence is quoted: systemic sclerosis (6 papers); antiphospholipid syndrome (5); autoimmune hepatitis (5); lupus erythematosus (4); primary biliary cholangitis (3); celiac disease (2); cerebral infarction (2); dacryoadenitis (2); erythema multiforme (2); hepatocellular carcinoma (2); Hypercholesterolemia (2); Hypertension (2); polyarthritis (2); Raynaud syndrome (2); sensory neuropathies (2); Splenomegaly (2); amyloidosis (1); angina (1); autoimmune encephalitis (1); autoimmune pancreatitis (1); autonomic dysfunction (1); bacterial infection (1); Basedow disease (1); Behcet’s syndrome (1); breast cancer (1); bundle branch block (1); cardiomyopathy (1); Cholecystitis (1); chronic hepatitis B (1); chronic myelogenous leukaemia (1).
A further 50 diseases each share a sentence with SSB in 1 paper.